KIR2DL1 (killer cell immunoglobulin like receptor, two Ig domains and long cytoplasmic tail 1)
Diseases named in the same sentence as KIR2DL1 in open-access papers (continued):
Sharing a sentence is not in itself a finding about the gene and the disease.
HIV-1 infection (2 papers, 2017 to 2022). The type species of lentivirus and the etiologic agent of acquired immunodeficiency syndrome (AIDS). "The frequency of KIR2DL1+ NK cells was linked to the number of the cognate HLA-C2 alleles, which we showed previously for individuals with primary HIV-1 infection." (PMID 35911762, 2022). "HIV-1 infection impaired KIR2DL1/DS1 expression in all the CD56dim subtypes." (PMID 28674534, 2017). "In recent years multiple studies have drawn attention to the potential role of HLA-C and its cognate inhibitory receptors, KIR2DL1, KIR2DL2, and KIR2DL3, in the intrinsic control of HIV-1 infection." (PMID 35911762, 2022). "Accumulating evidence indicated that interactions between HLA-C and its inhibitory KIR2DL receptors (KIR2DL1/L2/L3) can drive HIV-1-mediated immune evasion and thus may contribute to the intrinsic control of HIV-1 infection." (PMID 35911762, 2022).
lung carcinoma (2 papers, 2019 to 2023). "Our analysis revealed that the frequency of detection of olfactory receptor 52R1 and killer cell immunoglobulin-like receptor 2DL1 (KIR2DL1) negatively correlates with the spread of lung cancer cells in the lymph node." (PMID 37761972, 2023). "94.1% (48/51) patients had a direct correlation of down-regulated KIR2DL1 in lung cancer." (PMID 30934003, 2019).
lupus (2 papers, 2019 to 2020). "A recent study identified a penta-peptide (SKVVS) in the human papillomavirus (HPV) protein L1 that is shared with KIR2DL1, 2DL2, 3DL1, 3DL2, and 2DL4 and suggested that HPV infection in genetically predisposed individuals may contribute to lupus via molecular mimicry." (PMID 31572377, 2019).
myeloma (2 papers, 2015 to 2025). "Concurrent analysis of inhibitory receptors (KIR2DL1, KIR2DL2/3, KIR3DL1 and NKG2A) and NK cell degranulation upon co-culture with myeloma cells revealed that KIR–ligand-mismatched NK cells degranulate more than matched subsets and that HLA-E abrogates degranulation of NKG2A+ subsets." (PMID 25920521, 2015).
type 1 diabetes (2 papers, 2022 to 2025). "KIR2DL2 was associated with increased risk of type 1 diabetes whereas KIR2DL1 and KIR2DL5 decreased the risk of the latter." (PMID 35071606, 2022). "The multiple interactions of A*24:02 with two unique KIRs (KIR2DL1~2DP1~3DP1, 2DL4~3DL2~3DP1, where ‘~’ indicates equivalent KIR interactions) were found to have positive associations with type 1 diabetes progression." (PMID 40835749, 2025). "Considering the activating KIR2DL1 with ligand A*24:02, carriers of the HLA-I allele without KIR showed no progression to type 1 diabetes but those who carried the interaction experienced an incidence comparable with that in the two other groups." (PMID 40835749, 2025).
abortion (1 paper, 2023). the ending of pregnancy by removing a fetus or embryo before it can survive outside the uterus. "On the other hand, it has been pointed out that the stronger inhibitory interaction of KIR2DL1 + HLA-C2 affects placental development, causing reproductive problems such as pre-eclampsia, recurrent spontaneous abortion, and fetal growth restriction." (PMID 37760846, 2023).
acute leukemia (1 paper, 2021). A clonal (malignant) hematopoietic disorder with an acute onset, affecting the bone marrow and the peripheral blood. "This fact, however, seems less likely given that the negative effect of the KIR2DL1/HLA-C*04 interaction was observed in different lineages of acute leukemia, lymphoblastic (B and T), and myeloblastic." (PMID 34064810, 2021).
Autoimmunity (1 paper, 2019). The occurrence of an immune reaction against the organism's own cells or tissues. "Together, our findings suggest that KIR2DL1 isoforms co-evolved with HLA-C2 to enable differential detection of and response to target cells missing self HLA, while maintaining a dominant sensitivity for inhibition to avoid autoimmunity." (PMID 31024561, 2019).
cerebral malaria (1 paper, 2012). A sequestration of Plasmodium falciparum in the brain, which can cause coma and/or seizures. "Because the presence or absence of KIR2DL1 is a simple distinction of two centromeric KIR B regions and KIR2DL1 is in positive linkage disequilibrium with KIR2DL3, we also examined whether the presence or absence of KIR2DL1 in combination with HLA-C1 was associated with cerebral malaria." (PMID 22412373, 2012).
chronic hepatitis B infection (1 paper, 2018). "A recent study analyzed whether HLA-C and KIR genotypes were associated with treatment outcome for chronic hepatitis B infection (CHB) showing that the combination of KIR2DL1 with its ligand HLA-C2 is predictive of clinical outcome of infection predicted." (PMID 29707126, 2018).
Cirrhosis (1 paper, 2012). A chronic disorder of the liver in which liver tissue becomes scarred and is partially replaced by regenerative nodules and fibrotic tissue resulting in loss of liver function. "We found the KIR2DL1 gene expression high in patients with cirrhosis as compared to initial fibrosis stage." (PMID 22397681, 2012).
Encephalopathy (1 paper, 2023). Encephalopathy is a term that means brain disease, damage, or malfunction. "Except for KIR2DS4+, KIR2DS3+, and the inhibitor gene KIR2DL1+, which were found to be increased in patients with encephalopathy, it was found that the frequency of most KIR genes (activators and inhibitors) decreased in patients with encephalopathy who died from MF." (PMID 37046435, 2023).
Hodgkins lymphoma (1 paper, 2015). A heterogeneous group of malignant lymphoid neoplasms of B-cell origin characterized histologically by the presence of Hodgkin and Reed-Sternberg (HRS) cells in the vast majority of cases. "Genes KIR2DL1, KIR2DL3, KIR2DL5, and KIR2DS3/S5 were also present in our patients in haplotype motifs other than the classic cA01 (or KIR2DL1 and -2DL3) and cB01 (for the KIR2DL1, KIR2DL5, KIR2DS3, and KIR2DS5), as suggested for certain Hodgkin's lymphomas." (PMID 26495028, 2015).
kidney cancer (1 paper, 2019). Primary or metastatic malignant neoplasm involving the kidney. "91.7% (66/72) patients had a positive correlation of up-regulated KIR2DL1 in kidney cancer." (PMID 30934003, 2019).
lung squamous cell carcinoma (1 paper, 2023). "Another pan-cancer study revealed several single nucleotide variants affecting KIR2DL1, KIR2DL1 (MST/MaLR) downregulation associated with lung squamous cell carcinoma (LUSC)." (PMID 36979914, 2023).
oral cancer (1 paper, 2019). "KIR2DL1+-HLA-C2+ (human leukocyte antigen) genotype was found in oral cancer patients." (PMID 30934003, 2019).
osteosarcoma (1 paper, 2021). A usually aggressive malignant bone-forming mesenchymal neoplasm, predominantly affecting adolescents and young adults. "The osteosarcoma cell line lacking expression of HLA-C group 1 and 2 was efficiently lysed by NK cells from 2 donors lacking expression of KIR2DL1 or 3 major inhibitory KIRs (KIR2DL1, KIR2DL2/3, and KIR3DL1), respectively." (PMID 34199783, 2021).
pancreatic cancer (1 paper, 2014). "However, there was no significant change in the percentages of NK cells positive for activating surface receptors (NKp44 and NKp80) or inhibitory surface receptors (KIR3DL1 and KIR2DL1/DS1) with either of the pancreatic cancer cell lines." (PMID 25274283, 2014). "Two inhibitory surface receptors, KIR3DL1 and KIR2DL1/DS1, were investigated in this study, however we found no significant alteration in their expression in NK cells that following exposure to pancreatic cancer cells." (PMID 25274283, 2014).
parasitemia (1 paper, 2021). "The interaction of HLA-C*06:02 with the strongly inhibitory receptor KIR2DL1 likely influences NK cell education even in the absence of infection, leading to more potent NK cell function upon activation, although it is not evident how this would result in an increased risk of parasitemia." (PMID 33815410, 2021).
psoriatic arthritis (1 paper, 2011). Joint inflammation associated with psoriasis. "This conclusion concurs with previous reportsshowing a link between KIR2DS1 and KIR2DS2 andrisk for developing psoriatic arthritis, particularly in the absence of the HLAligands for their homologous inhibitory receptors, KIR2DL1 and KIR2DL2/3." (PMID 21347267, 2011).
thyroid cancer (1 paper, 2018). "However, none of the thyroid cancer cell culture supernatants altered the expression levels of NK cell inhibitory receptors such as killer cell immunoglobulin-like receptor (KIR)2DL1 and KIR2DL3." (PMID 30140269, 2018).
ulcerative colitis (1 paper, 2014). An inflammatory bowel disease involving the mucosal surface of the large intestine and rectum. "In this context, the frequency of KIR2DL1 and KIR2DL3 genotypes was shown to be lower in ulcerative colitis patients as compared to control individuals." (PMID 25310588, 2014).
tumor (41 papers, 2010 to 2025). "KIR2DL1-mediated immunosuppression is one of the causes of tumour immune escape and a major obstacle to successful tumour immunotherapy." (PMID 34935568, 2022). "Inhibitory KIRs (like KIR2DL1) are linked to immune tolerance but may impair anti-tumor immunity." (PMID 40244151, 2025). "These cells were also clearly distinct from the tumor-associated CD69+IFNG+PRF1– and the dysfunctional/low cytotoxic NR4A1+ CD158a (KIR2DL1)+ CD158e (KIR3DL1)+ NK cell populations described in the other studies." (PMID 40530504, 2025). "KIR2DL1 was expressed in 3.93 ± 0.18% (mean ± SD converted log2) and 3.81 ± 0.17% of non-tumor and GBM tissue, respectively." (PMID 37762486, 2023). "Fn + CD8+KIR2DL1 positivity was obviously correlated with deep tumour invasion, positive lymph node metastasis, and more advanced clinical stage." (PMID 34935568, 2022). "On the whole, gene expression profile of KIR2DL1/S1+ CD8+ cells defines a T cell subset with high anti-tumor potential that remains in a resting state after the in vitro expansion." (PMID 33076479, 2020). "For example, Lirilumab (IPH2102) blocks KIR2DL1/2DL2/2DL3 and boosts NK-cell anti-tumor activity." (PMID 40244151, 2025). "Analysis of our previously published RNA-Seq dataset, which includes various cell types found in OC ascites and omental metastases, showed selective expression of KIR2DL1, KIR2DL4, and NCR1 in tumor-associated NK cells (TANK), and KLRK1 and NCR3 in both TANK and tumor-associated T cells (TAT)." (PMID 39563446, 2024). "Moreover, KIR2DL1 expression tends to be lower in GBM tissue than in non-tumor tissue, as demonstrated by the GlioVis data portal and TCGA database." (PMID 37762486, 2023). "KIR2DL1/S1+NKT-like cells were increased in tumor specimens when compared with their level in PF." (PMID 36560531, 2022). "Furthermore, reduced expression of NKG2C, NKG2D, CD161, KIR2DL2/L3/S3, and KIR2DL1/S1 on CD56DimNK cells likely reflects the exhaustion of NK cells in tumor specimens." (PMID 36560531, 2022). "In addition, KCNN4 demonstrates a negative correlation with CD160, KDR, and KIR2DL1, which are associated with NK and T‐cell activation, as well as tumour angiogenesis." (PMID 40952239, 2025). "Similarly in GiNKs, stimulation from KIR2DL1, which is typically an inhibitory system, contributes to NK cell activation, and inhibiting KIR2DL1 might have attenuated the anti-tumor effect of NK cells against GBM." (PMID 37762486, 2023). "Thus, individuals who have the KIR AA genotype in this population likely have two genomic copies of the strongly inhibiting KIR2DL1 allotype, KIR2DL1*003, and should be best equipped at recognizing and eliminating tumor cells having aberrant C2+HLA-C expression." (PMID 31379844, 2019). "Both anti-KIR2DL1/2/3-mAb-IgG423 and anti-NKG2A-mAb-IgG426 have demonstrated the enhancement of NK-mediated ADCC and anti-tumor immunity." (PMID 38272918, 2024). "The anti-KIR2DL1/2/3-mAb-IgG4 targets inhibitory KIR2DL1/2/3 receptors on NK cells and blocks their interaction with human leukocyte antigen (HLA)-C (classical MHC-I), thereby enhancing NK-mediated anti-tumor activity." (PMID 38272918, 2024). "In our scRNA-seq data, NK cells in tumor tissue showed higher expression of NKG2A and KIRs, including KIR2DL1, on a larger percentage of NK cells in patients with less pathological regression, suggesting that these subsets impair responses to anti-PD-L1." (PMID 36097216, 2022). "In tumor tissue, NKG2A and KIRs, including KIR2DL1, were predominantly expressed on NK cells; these receptors were more highly expressed on a greater percentage of NK cells in patients with lesser pathological regression." (PMID 36097216, 2022). "The expression of KIR2DL1 on CD8+ T cells plays an important role in regulating the immune response and is positively correlated with the occurrence and development of tumours." (PMID 34935568, 2022).
tumor (continued). "KIR2DL1/S1+ CD8+ T cells show over-expression of components of the FcεRI and NCR3 signaling pathways, genes which play an important role in tumor killing by T and NK cells." (PMID 33076479, 2020). "In patients who survive long periods after the cytoreductive therapy, HLA C2-ligands favor the expansion of KIR2DL1+ CD8+ T cells, which show a gene expression signature related to efficient tumor immunosurveillance." (PMID 33076479, 2020). "It has been found that in tumor cells, immune checkpoints can lead to NK cell dysfunction, blocking these immune checkpoints (e.g. TIM-3, NKG2A, CTLA-4, PD-1, KIR2DL-1/2/3, CD96, TIGIT) can restore the function of NK cells." (PMID 33614486, 2020). "Additionally, an array of specific NK inhibitory markers, namely KIR2DL1, KIR2DL3, and KIR2DL4, were elevated, indicative of tumor-induced NK cell suppression." (PMID 40547037, 2025). "Cluster3 of both subsets (which we refer to as NK-innate-likeCD28− and CD28+, respectively), represented in peripheral blood and reduced at the tumor site, were characterized by the expression of NK-like markers KLRB1, KLRC3, and KIR2DL1, along with IKZF2 and ZBTB16 (PLZF)." (PMID 37898752, 2023). "Further analysis revealed significantly reduced percentages of CD159a/NKG2A+ CD56dim and CD56brightNK-cells within tumor tissue when compared to peripheral blood of GBM patients, whereas the percentages of CD158a/KIR2DL-1+ and CD158b/KIR2DL-2/3+ CD56dim and CD56bright NK-cells were not different." (PMID 35474089, 2022). "Moreover, we observed an increased fraction of NK-cells with preferential expression of CD158ab/KIR2DL-1,-2/3, and downregulation of CD159a/NKG2A within the tumor tissue." (PMID 35474089, 2022). "Two HLA-C2/C2 tumor lines, BJAB (Burkitt-like lymphoma) and HL-60 (AML), displayed significant levels of HLA-C2 as assessed by KIR2DL1-Fc binding, and high rates of killing could be observed in the mismatched setting." (PMID 36319065, 2022). "In conclusion, Fn may induce high expression of KIR2DL1 on the surface of CD8+ T cells in ESCC tissues to provide a favourable microenvironment for self-sustaining infection, thus promoting tumour progression." (PMID 34935568, 2022). "Fn may induce high expression of KIR2DL1 on the surface of CD8+ T cells to inhibit the immune response and induce tumour cell immune escape." (PMID 34935568, 2022). "The KIR-HLA-ligand-matched KIR2DL1+ single-positive NK cell subset did not degranulate against those mouse-derived tumor cells, while the mismatched KIR2DL2/3+ and KIR3DL1+ single-positive populations degranulated." (PMID 34203549, 2021). "Interestingly, both inhibitory KIR (KIR2DL1, KIR2DL3 and KIR3DL1) and activating KIR (KIR2DS1 and KIR2DS4) were reduced in expression when effectors were exposed to tumor in the presence of TriKE." (PMID 32961861, 2020). "KIR2DL1/S1+ CD8+ T cells showed a gene expression signature related to efficient tumor immunosurveillance, whereas KIR2DL2/L3/S2+CD8+ T cells showed transcriptomic profiles related to suppressive anti-tumor responses." (PMID 33076479, 2020). "Thus, in patients who survived long periods after the cytoreductive therapy, HLA C2-ligands favored the expansion of KIR2DL1+ CD8+ T cells, which showed a gene expression signature related to efficient tumor immunosurveillance." (PMID 33076479, 2020). "Indeed, we confirmed lower expression of KIR2DL1 on CAR MLNK cells, which might unleash them from KIR/HLA-I inhibition and thus enhance killing of CD19+ tumor cells." (PMID 37207215, 2023). "KIR2DL1 and KIR2DL2 expression did not demonstrate differences between GBM and non-tumor samples in TCGA database (p = 0.08 and 0.69, respectively), while KIR2DL3 expression demonstrated differences (p < 0.01)." (PMID 37762486, 2023). "Interestingly, CXCL6 and other ARGs also showed negative correlations with checkpoints like VEGFB, KIR2DL1, LAG3, CTLA4, PDCD1, and IFNG, indicating they may promote immune surveillance and anti-tumor responses." (PMID 40943183, 2025).
cancer (13 papers, 2017 to 2025). A tumor composed of atypical neoplastic, often pleomorphic cells that invade other tissues. "These antibodies bind to KIR2DL1/2/3, blocking their association with HLA and enhancing the cytotoxicity of NK cells against cancer cells." (PMID 41023081, 2025). "Analysis of data from The Cancer Genome Atlas and Genotype‐Tissue Expression databases revealed that KIR2DL1, KIR2DL3 and KIR2DL4 expression were significantly upregulated in AML and associated with decreased overall survival (OS)." (PMID 38527290, 2024). "further confirmed that stronger KIR2DL1 signaling was more potent than the weaker in licensing NK cells, resulting in better cancer control and patient survival after transplantation." (PMID 39148728, 2024). "There is scarce knowledge in KIR2DL1 and KIR3DL3 association with cancers." (PMID 35652109, 2022). "In addition, the expression of KIR2DL1 on the surface of CD8+ T cells in cancer tissues was consistent with Fn infection in cancer tissues, suggesting that the immune microenvironment of cancer tissue is more conducive to Fn survival." (PMID 34935568, 2022). "Our results show that nsSNVs found in multiple cancer types are located within exomes of TNN, KIR2DL1, OR4K15, and ZNF99 genes." (PMID 30934003, 2019). "Immunostimulators KIR2DL1 and KIR2DL3 lack sufficient data in most cancers." (PMID 39830645, 2024). "Inhibitory KIR (such as KIR2DL1, KILR2DL2, KIR2DL3 and KIR3DL1) interaction with its ligand may protect cancer cells from NK cell-mediated killing." (PMID 36817482, 2023). "Also, we observed that USP5 was correlated with most immune inhibitors and immune stimulators except for KIR2DL1, KIR2DL3 and TNFSF18 in pan-cancer." (PMID 37268697, 2023). "However, the presence of HLA C2-ligands was associated with a higher frequency of KIR2DL1+ NK cells (8.88 vs. 4.23, p < 0.01), a difference that persisted in all groups of cancer patients regardless of whether they survived or succumbed to the disease during follow-up." (PMID 33076479, 2020). "The expansion of KIR2DL1+ CD8+ T cells induced by its specific C2-ligand was observed in healthy controls and in patients who survived the monitoring periodwith any of the three types of cancer analyzed." (PMID 33076479, 2020).